LINC00852 (long independently transcribed non-coding RNA 852)
Synonyms: NAG73; GHRL-AS2; C3orf42; GHRLOS2
Gene: Long non-coding RNA gene on chromosome 3 (10,284,419 to 10,285,746, forward strand). Ensembl gene ENSG00000231177.
Diseases named in the same sentence as LINC00852 in open-access papers:
LINC00852 is named in the same sentence as 12 diseases in open-access papers, as found by Europe PMC text mining. Sharing a sentence is not in itself a finding about the gene and the disease. The quoted sentences say what the papers report.
osteosarcoma (6 papers, 2020 to 2025). A usually aggressive malignant bone-forming mesenchymal neoplasm, predominantly affecting adolescents and young adults. "Clinically, linc00852 was significantly highly expressed in osteosarcoma tissues and positively associated with tumor volumes and metastases, which was also obviously related with AXL mRNA expression." (PMID 32673448, 2020). "Taken together, linc00852 significantly increased in osteosarcoma tissues, and it was positively associated with tumor volume, metastasis, and the expression of AXL mRNA, and it functioned as an oncogene to facilitate osteosarcoma initiation and development." (PMID 32673448, 2020). "AXL‐associated exosomal linc00852 up‐regulated the proliferation, migration, and invasion of osteosarcoma cells, which would be considered as a new tumor biomarker and a special therapeutic target for osteosarcoma." (PMID 32673448, 2020). "Increased expression of linc00852 caused AXL and AKT overexpression, indicating that linc00852 could promote the progression of osteosarcoma cells through the AXL‐AKT pathway." (PMID 32673448, 2020). "In osteosarcoma cell-lines (like 143B and MG-63), it is observed that LINC00852 acts as a transcription factor and increase the expression of AXL gene." (PMID 40491847, 2025). "FISH assay in 143B and MG63 demonstrated that linc00852 was mainly located in the nucleus of osteosarcoma cells." (PMID 32673448, 2020). "Then, linc00852 was confirmed by qRT‐PCR to be highly expressed in osteosarcoma cell lines as 143B, HOS, MG63, U2OS, and SAOS2, which were significantly higher than that in the NIH3T3 cells." (PMID 32673448, 2020). "In this study, we have proven that exosomal linc00852 plays as a pivotal identified intercellular messenger in osteosarcoma." (PMID 32673448, 2020). "To investigate the exact function of linc00852 in osteosarcoma cells, we ectopically increased the linc00852 level using lentiviral vectors in 143B and HOS cells and suppressed linc00852 expression using lentiviral shRNAs." (PMID 32673448, 2020). "Cox's proportional hazards regression demonstrated that highly expressed linc00852 was an independent predictor of the prognosis for the osteosarcoma patients." (PMID 32673448, 2020). "In addition, a recent study has shown that LINC00852 expression is up-regulated in osteosarcoma and promotes the proliferation, migration, and invasion of osteosarcoma cancer cells." (PMID 34496800, 2021). "Moreover, LINC00852 can act as a ceRNA and competitively binding to miR-7-5p to exert its function in osteosarcoma." (PMID 34496800, 2021). "A positive feedback loop between exosome derived linc00852 and AXL demonstrated that exosome derived linc00852 may act a novel osteosarcoma biomarker." (PMID 34712664, 2021). "Exosomal linc00852 promotes osteosarcoma migration and invasion by upregulating AXL." (PMID 32673448, 2020). "Furthermore, linc00852 was especially highly expressed in the poorly differentiated osteosarcoma cell lines as 143B and HOS, which were 3.4 and 2.5 times higher than that in NIH3T3 cells, separately(P = .000, HOS; P = .000)." (PMID 32673448, 2020). "We also illustrated that overexpression of linc00852 was positively associated with AXL mRNA and showed a negative relationship with miR‐7‐5p, which strongly revealed that a regulatory network existed between these three factors in osteosarcoma." (PMID 32673448, 2020). "As shown by the growth curve of the xenograft tumors, the tumor volume of linc00852 overexpressed group was three times bigger than that of the control group, which indicated that linc00852 overexpression also increased the osteosarcoma cells’ growth and invasion in vivo (P = .000)." (PMID 32673448, 2020). "Linc00852 increased AXL expression and promoted the progression of osteosarcoma through the AXL‐AKT pathway." (PMID 32673448, 2020).
osteosarcoma (continued). "According to the qRT‐PCR analysis, the level of linc00852 in osteosarcoma tissues was almost 10 times higher than that in adjacent nontumor tissues of 34 patients (P = .000)." (PMID 32673448, 2020). "Thus, we demonstrated a positive feedback loop that regulates exosomal linc00852 and AXL in osteosarcoma." (PMID 32673448, 2020). "In conclusion, our study demonstrated that osteosarcoma cells with high AXL expression promoted growth, invasion and metastasis of the other tumor cells with low AXL expression through releasing linc00852‐containing exosomes and a positive feedback regulation loop between AXL and exosomal linc00852." (PMID 32673448, 2020).
lung adenocarcinoma (3 papers, 2020 to 2022). A carcinoma that arises from the lung and is characterized by the presence of malignant glandular epithelial cells. "LINC00852 was up-regulated in lung adenocarcinoma spinal metastases and lung adenocarcinoma cells, and LINC00852 overexpression promoted the proliferation and inhibited the apoptosis of lung adenocarcinoma cells in vitro." (PMID 34496800, 2021). "LINC00852 is overexpressed in lung adenocarcinoma spinal metastasis tissues and functions as an oncogene by promoting the proliferation, migration, and invasion of lung adenocarcinoma cells." (PMID 34496800, 2021). "Until now, only one study has been conducted on linc00852, which promote lung adenocarcinoma progression and spinal metastasis by activating MAPK pathway." (PMID 32673448, 2020). "In addition, in vivo, and in vitro experiments have shown that the target gene S100A9 of LINC00852 has a positive regulatory effect on the growth, migration, invasion, and metastasis of lung adenocarcinoma cells." (PMID 36465402, 2022). "Linc00852 and MAPK pathways were associated with lung adenocarcinoma SM." (PMID 36465402, 2022).
lung carcinoma (2 papers, 2024 to 2025). "This mirrors literature reports that LINC00852 can be cytoplasmically enriched in lung carcinoma cases." (PMID 40491847, 2025). "The pan-cancer analysis performed in the current study through the GENT2 database demonstrated a significant upregulation of LINC00852 in lung cancer, and its remarkable downregulation in many tumors including breast cancer." (PMID 39557729, 2024). "In lung carcinoma cell-lines (A549 and SPCA-1), LINC00852 was found mainly in the cytoplasm (qRT-PCR assay)." (PMID 40491847, 2025). "In our analysis LINC00852 showed a marked cell-line–specific shift–predominantly nuclear (negative localization score) in most cell types, but strongly cytoplasmic in the NCI-H460 lung carcinoma line." (PMID 40491847, 2025).
prostate carcinoma (2 papers, 2022 to 2025). A carcinoma that arises from epithelial cells of the prostate gland. "It has been reported that LINC00852 is highly expressed in prostate cancer tissues, and lentivirus-mediated overexpression of LINC00852 significantly improves the proliferation, migration and invasion capabilities of the prostate cancer cells." (PMID 36471281, 2022). "And LINC00852 was also highly expressed in prostate cancer cell lines compared to normal prostate epithelial cells RWPE-1." (PMID 36471281, 2022). "The results of correlation analysis showed that the expression levels of miR-29a-3p and LINC00852 in prostate cancer tissues were negatively correlated." (PMID 36471281, 2022). "In this study, we confirmed the binding of LINC00852 with miR-29a-3p using dual-luciferase reporter gene assay, and LINC00852 negatively regulated miR-29a-3p in prostate cancer cells." (PMID 36471281, 2022). "Overexpression of LINC00852 significantly promoted the migration and invasion of prostate cancer cells, while knockdown of LINC00852 significantly inhibited the migration and invasion of prostate cancer cells in vitro." (PMID 36471281, 2022). "In this study, we probed the mechanism of LINC00852 in promoting the proliferation, migration and invasion of prostate cancer cells, which provided a theoretical basis of LINC00852 as a drug target for prostate cancer treatment." (PMID 36471281, 2022). "To investigate the function of LINC00852 in prostate cancer, we tested the expression level of LNC00852 in prostate cancer tissues, and cell lines including LNCaP, VCaP, PC-3 and normal prostate epithelial cells (RWPE-1)." (PMID 36471281, 2022). "Furthermore, numerous lncRNAs modulate cellular activities by regulating miR-29a-3p; for instance, LINC00852 modulates prostate cancer cell proliferation and invasion by regulating the MiR-29a-3p/JARID2 axis." (PMID 40652273, 2025). "In summary, we demonstrated that LINC00852 played a key role in promoting the prostate cancer, and LINC00852/miR-29a-3p/JARID2 axis could be used as a target for prostate cancer treatment." (PMID 36471281, 2022). "Overexpression of LINC00852 could increase the expression of JARID2 in prostate cancer cells, and miR-29a-3p mimics reversed the cell promotion under overexpression of LINC00852 through targeting on JARID2 in prostate cancer cells." (PMID 36471281, 2022). "Moreover, silencing JARID2 reversed the proliferation, migration and invasion of prostate cancer cells by overexpression of LINC00852." (PMID 36471281, 2022). "Collectively, our results indicated that the LINC00852/miR-29a-3p/JARID2 axis might play a key role in the progression of prostate cancer." (PMID 36471281, 2022). "Thus, LINC00852 is a promising target for the treatment of prostate cancer." (PMID 36471281, 2022). "In summary, LINC00852 may act as ceRNA and sponge miR-29a-3p in prostate cancer cells." (PMID 36471281, 2022). "Furthermore, we confirmed whether LINC00852 could regulate the proliferation and invasion of prostate cancer cells through binding miR-29a-3p." (PMID 36471281, 2022). "In summary, overexpression of LINC00852 might promote the proliferation, invasion and migration of prostate cancer cells through miR-29a-3p/JARID2 axis, and the knock-down of LINC00852 could reverse this phenotype." (PMID 36471281, 2022). "In addition, overexpression of LINC00852 was only proved to regulate the biologic processes in prostate cancer cell, while the detailed mechanism was not fully demonstrated." (PMID 36471281, 2022).
breast carcinoma (1 paper, 2024). "In the present study, we used several online tools to examine the importance of LINC00852 in the pathoetiology of breast cancer." (PMID 39557729, 2024). "Upon analyzing the OS of breast cancer patients, specifically focusing on the median expression of LINC00852, our investigation encompassed data obtained from various databases including ENCORI/starBase, Kaplan–Meier Plotter, and GSCA." (PMID 39557729, 2024). "The article provides a detailed analysis of LINC00852 as a potential biomarker in breast cancer, with an emphasis on its roles in tumorigenesis, metastasis, and chemoresistance." (PMID 39557729, 2024). "In brief, LINC00852/miR-145-5p axis is a possible functional axis in the pathogenesis of breast cancer." (PMID 39557729, 2024). "In the current study, we used several online tools to examine the importance of LINC00852 in breast cancer." (PMID 39557729, 2024). "Furthermore, the bc-GenExMiner v5.1 data indicated a significant downregulation of LINC00852 expression in breast cancer stages 2 and 3 compared to stage 1." (PMID 39557729, 2024). "Thus, the result of present study regarding down-regulation of LINC00852 in breast cancer is consistent with the proposed ceRNA network between these two transcripts." (PMID 39557729, 2024). "We also measured the expression of LINC00852 in the tumor and non-tumor tissues of breast cancer patients." (PMID 39557729, 2024). "Yet, function of LINC00852 in breast cancer is not comprehensively clear." (PMID 39557729, 2024).
gastric cancer (1 paper, 2021). A primary or metastatic malignant neoplasm involving the stomach. "LINC00852, also known as nasopharyngeal carcinoma related gene NAG73, C3orf42, ghrelin opposite strand/antisense RNA (GHRLOS), and GHRL-AS2, can be highly expressed in cancer tissues and cancer cells, such as gastric cancer and thyroid cancer." (PMID 34496800, 2021).
ovarian carcinoma (1 paper, 2021). A malignant neoplasm originating from the surface ovarian epithelium. "We found that LINC00852 expression was significantly up-regulated in ovarian cancer tissues and cells, whereas miR-140-3p expression was significantly down-regulated in ovarian cancer tissues." (PMID 34496800, 2021). "Since SK-OV3 and OV-90 cells are commonly used in the study of the growth and invasion in ovarian cancer and LINC00852 expression is highly expressed in SKOV-3 and OV-90 cells, we use SKOV-3 and OV-90 cells for the following experiments." (PMID 34496800, 2021). "Dual luciferase reporter gene assay together with RIP assay and RNA pull down assay showed that miR-140-3p was a downstream molecule of LINC00852, and LINC00852 acted as a sponge for miR-140-3p in ovarian cancer cells." (PMID 34496800, 2021). "Functionally, LINC00852 knockdown inhibited the viability, proliferation and invasion of ovarian cancer cells, and promoted the apoptosis of ovarian cancer cells." (PMID 34496800, 2021). "So, it is meaningful for identifying the role of LINC00852 in the regulation of ovarian cancer progression." (PMID 34496800, 2021). "Importantly, the analysis of LINC00852 expression and clinicopathological characteristics of ovarian cancer showed that LINC00852 expression was correlated with TNM stage and lymph node metastasis." (PMID 34496800, 2021). "Besides, LINC00852 expression was significantly up-regulated in human ovarian cancer cells (A2780, SKOV-3, OV-90 and CAOV3) than normal human ovarian epithelial cells IOSE80, with highest LINC00852 expression in SKOV-3 cells." (PMID 34496800, 2021). "Therefore, we first identified that LINC00852 was up-regulated in ovarian cancer, which might play vital roles in the progression of ovarian cancer." (PMID 34496800, 2021). "Finally, LINC00852 knockdown inhibited the growth and invasion ovarian cancer in vivo." (PMID 34496800, 2021). "In the present study, we investigated the role of LINC00852/miR-140-3p/AGTR1 pathway in ovarian cancer, and found LINC00852 acted as a ceRNA of miR-140-3p to repress miR-140-3p expression thereby promoting AGTR1 expression to promote the growth and invasion of ovarian cancer in vitro and in vivo." (PMID 34496800, 2021). "However, whether LINC00852 modulates the proliferation, migration, and invasion of ovarian cancer is not discovered." (PMID 34496800, 2021). "However, whether LINC00852 acts as oncogene or tumor suppressing gene in ovarian cancer is not clear." (PMID 34496800, 2021).
cancer (5 papers, 2021 to 2025). A tumor composed of atypical neoplastic, often pleomorphic cells that invade other tissues. "Based on the target prediction using bioinformatics analysis, LINC00852 was predicted as ceRNA of miR-29a-3p, and the miR-29a-3p has been proved as a tumor suppressor in a variety of cancers from previous studies." (PMID 36471281, 2022). "The fact that LINC00852 is cytoplasmic in some cancer lines but nuclear in others suggests it may switch roles-in cytosolic form it may acts as a post-transcriptional regulator (e.g., miRNA sponge), whereas nuclear retention may imply transcriptional or chromatin-related roles." (PMID 40491847, 2025).
tumor (5 papers, 2019 to 2024). "In this study, we found that the loss of LINC00852 significantly reduced tumor volume and tumor weight in a SKOV-3 xenograft mouse model." (PMID 34496800, 2021). "The results showed that overexpression of LINC00852 promoted the growth of transplanted tumor, and the knockdown of LINC00852 had an inhibitory effect on the growth of transplanted tumor." (PMID 36471281, 2022). "Studies have revealed that AATBC, ADAMTSL4-AS1, EPB41L4A-AS1, MIA-RAB4B, MIR4697HG, GAS5, SNHG12, MSX2P1, and LINC00852 are related to tumorigenesis and tumor progression in multiple cancers, such as bladder, breast, colorectal, and ovarian." (PMID 31850068, 2019). "Furthermore, the expression of LINC00852 was downregulated in tumor tissues when compared to tumor-adjacent tissues." (PMID 39557729, 2024). "Besides, the loss of LINC00852 significantly increased miR-140-3p expression, reduced AGTR1 expression and inhibited the activation of MEK/ERK/STAT3 pathway in tumor tissues from SKOV-3 xenograft mice." (PMID 34496800, 2021). "Expression levels of LINC00852 were not correlated with any of clinicopathological features including age, tumor diameter, invasion to lymph, grade, stage, expression of hormone receptors, HER2 levels, KI67 levels or family history of this malignancy." (PMID 39557729, 2024).
LINC00852 also shares sentences with these, for which no sentence is quoted: acute myeloid leukemia (1 paper); nasopharyngeal carcinoma (1); thyroid cancer (1).